APOC3 (apolipoprotein C3)
Diseases named in the same sentence as APOC3 in open-access papers (continued):
Sharing a sentence is not in itself a finding about the gene and the disease.
dyslipidemia (continued). "In conclusion, PCSK9, apoC3, and sdLDL-C showed significant interactions with current dyslipidemias, and were predictive in the screening." (PMID 27713142, 2017). "Further, of the two upstream variants from APOC3 (rs2854116) and APOA1 (rs632153) that were associated with the disease, only APOA1 is risk conferring towards dyslipidemia." (PMID 28610615, 2017). "Despite the interactions, a high degree of discordances of PCSK9, apoC3, and sdLDL-C with current dyslipidemias were detected." (PMID 27713142, 2017). "In polytomous logistic regression models, we analyzed the interactions of the elevated PCSK9, apoC3, and sdLDL-C levels with increasing dyslipidemias." (PMID 27713142, 2017). "Third, we evaluated the discordances of PCSK9, apoC3, and sdLDL-C with current dyslipidemias, and found substantial discordances exist in each dylipidemia group and normalipidemia patients." (PMID 27713142, 2017). "APOC3 (Apolipoprotein C3, located on chromosome 11q23.3) is critical for triglyceride metabolism and a potential therapeutic target for metabolic syndrome." (PMID 27060904, 2016). "In patients with metabolic syndrome, the most extensively glycosylated (di-sialylated) isoform of apoC3 was reduced in VLDL, LDL, and HDL fractions by 17%, 30%, and 25%, respectively (p<0.01 vs. controls for all)." (PMID 25118169, 2014). "Since the APOC3 and APOA5 SNPs are in different haplotype blocks, the association with metabolic syndrome was tested for the two blocks independently." (PMID 18789138, 2008). "Collectively, APOC3 can beconsidered as a suitable target for management of dyslipidemia." (PMID 39228490, 2024). "When HDL contains APOC3, the effectiveness of RCT is diminished, which may explain why HDL with APOC3 is associated with dyslipidemia, obesity, and CHD." (PMID 39684468, 2024). "Therefore, in this study, we selected rs12137855 in the LYPLAL1 gene, rs2854116 in the APOC3 gene and rs4880 in the SOD2 gene to investigate the association of three gene polymorphism, OS and their interaction with dyslipidemia." (PMID 36759651, 2023). "SNPs in the apolipoprotein A1 and C3 (APOA1 and APOC3) genes and cluster of differentiation 36 (CD36) gene led to increased risk of metabolic syndrome in subjects with Western dietary pattern and dyslipidemia in individuals who consumed high amounts of fat, respectively." (PMID 37610590, 2023). "The present findings suggest that the regulatory impact of E2 on ApoC3 expression may be selectively induced in the context of dyslipidemia." (PMID 36855114, 2023). "Apolipoprotein H (ApoH), also known as β2-glycoprotein I (β2GPI) is a phospholipid-binding plasma protein that is involved in lipid metabolism, angiogenesis and atherogenesis, among others, whereas APOC3 or ApoC-III is an important regulator of triglyceride transport and dyslipidemia." (PMID 34359627, 2021). "Substantial discordances with PCSK9, apoC3, and sdLDL-C in each dyslipidemia group were observed." (PMID 27713142, 2017). "Four common SNPs in the APOC3 gene, rs2854116, rs2854117, rs4520 and rs5128, have been identified as putative functional SNPs that influence serum APOC3 concentrations and result in dyslipidemia by influencing triglyceride (TG) and very-low-density lipoprotein (VLDL) levels." (PMID 27690381, 2016). "Rs5128 might facilitate microRNA binding and change the transcriptional activity of APOC3, leading to higher plasma APOC3 levels and dyslipidemia." (PMID 27690381, 2016). "Although the APOC3 genotype may still contribute to cholesterol levels after a long-term exposure, dyslipidemia attributed to HAART would be strong enough to conceal subtle genotype differences." (PMID 22848358, 2012). "They thought that the ApoC3 3238C>G polymorphism is not major contributors to the risk of dyslipidemia in the population of northern France." (PMID 21854571, 2011).
dyslipidemia (continued). "In contrast, the APOC3 -482C>T and APOC3 3238C>G SNPs did not significantly affect the risk of metabolic syndrome in this sample of French origin, despite significant association with triglyceride level." (PMID 18789138, 2008). "In contrast, haplotype analyses with the two APOC3 SNPs did not reveal any significant association with metabolic syndrome." (PMID 18789138, 2008). "Additionally, 4 genes (APOB, INSR, PPARG, APOC3) had prior genetic associations with MASLD while another 12 genes had associations with a MASLD-related phenotype (type 2 diabetes, BMI-adjusted waist-to-hip ratio (WHRadjBMI), metabolic syndrome)." (PMID 40065360, 2025). "Other innovative lipid-modifying approaches include antisense oligonucleotides targeting apolipoprotein C3, angiopoietin-like protein 3, and lipoprotein(a) [Lp(a)]—such as pelacarsen and olpasiran—which demonstrate promising results in addressing genetically driven dyslipidemias." (PMID 40593368, 2025). "Moreover, an in-depth analysis of the standard position of the APOC3 gene may address dyslipidemia and provide a cure for CVDs." (PMID 39684468, 2024). "Thus, ApoC3 is considered as a powerful risk indicator for CVD risk and dyslipidemia." (PMID 36050800, 2022). "Particularly, the variants rs632153, rs633389, rs2187126 and rs1263163 might be risk conferring to dyslipidemia by elevating LDLC and TC levels, while the variants of APOC3 and APOA1 genes might be the genetic determinants of elevated triglycerides in the present population." (PMID 28610615, 2017). "Furthermore, discordances of PCSK9, apoC3, and sdLDL-C with current dyslipidemias were observed." (PMID 27713142, 2017). "Mainly present in genes of lipid metabolic pathways (APOA5, APOB, APOC3 and LPL), the higher frequency of risk alleles in Puerto Ricans has been associated previously in other populations with unfavorable lipid profile and insulin response, cardiovascular conditions and metabolic syndrome." (PMID 19682384, 2009). "Nonetheless, our data are consistent with the concept that APOC3 genotype may have a direct or indirect mechanistic role in the development of dyslipidemia and progression of MetS, and are in line with the recent report of a significant association with MetS in a small multi-ethnic study group." (PMID 18096054, 2007). "Unlike the contradictory data from the LPL activator, abrogating the inhibitory effects of ApoC3 and ANGPTLs on LPL activity consistently reduces circulating TG levels, thus yielding promising outcomes of dyslipidemia in different experimental animal models." (PMID 35187136, 2022). "The recently observed association between the APOC3-related rs10892151 polymorphism and serum triglyceride levels has prompted us the possibility to explore whether this genetic variant may play a major role in human immunodeficiency virus (HIV)/antiretroviral therapy-induced dyslipidemia." (PMID 21939545, 2011). "The effect of APOC3 has been previously tested in a mouse model of DKD without human-like dyslipidemia." (PMID 38743496, 2024). "A multivariable analysis was performed to assess whether the ANGPTL4, ApoC3, and LPL axis was altered in RA and to study its relationship with RA dyslipidemia and subclinical carotid atherosclerosis." (PMID 35488290, 2022). "In contrast, the APOC3 -482C>T and 3238C>G SNPs did not appear to be related to metabolic syndrome in this French sample." (PMID 18789138, 2008). "It was, therefore, the purpose of the present study to investigate the interactions of PCSK9, apoC3, and sdLDL-C with current dyslipidemias, and identify their levels in predicting dyslipidemias in a large cohort of Chinese non-treated patients undergoing coronary angiography (CAG)." (PMID 27713142, 2017).
dyslipidemia (continued). "Although prior studies have explored possible correlations of PCSK9, apoC3, and sdLDL-C with lipid profile, including TG, LDL-C, and HDL-C, and their role in atherogenisis, few of them assessed the role of these parameters in determining current dyslipidemias and compared the discordance." (PMID 27713142, 2017).
Insulin resistance (90 papers, 2007 to 2025). Increased resistance towards insulin, that is, diminished effectiveness of insulin in reducing blood glucose levels. "Previous research has shown an independent association between APOC3, insulin resistance, and β-cell dysfunction in RA patients." (PMID 38416767, 2024). "Dysregulation of lipid metabolism, which is characterized by elevated levels of triglycerides and APOC3, is associated with metabolic disorders such as obesity, insulin resistance, and cardiovascular disease." (PMID 39479684, 2024). "Elevated ApoC3 levels have been associated with various disorders, including metabolic syndrome and insulin resistance in vivo." (PMID 38441531, 2024). "A study of ob/ob mice showed that insulin resistance accelerated the secretion of APOC3, which consequently caused inflammation of the islet cells as well as increased mitochondrial metabolism, free cytoplasmic calcium ions, and apoptosis." (PMID 39684468, 2024). "Apolipoprotein C3 (APOC3), another protein mainly produced in the liver, has been linked to insulin resistance and NAFLD progression in certain populations due to specific gene polymorphisms." (PMID 39408924, 2024). "In conclusion, ApoC3, insulin resistance, and beta-cell dysfunction are independently associated in patients with RA." (PMID 35637531, 2022). "Apolipoprotein C-III (ApoC3) has been associated with such insulin resistance and beta-cell dysfunction in the general population." (PMID 35637531, 2022). "A multivariable regression analysis was performed to study the relationship of ApoC3 with those molecules and indices adjusting for classic factors associated with insulin resistance that included glucocorticoids." (PMID 35637531, 2022). "In humans, increased circulating APOC3 levels are associated with cardiovascular disorders, inflammation, and insulin resistance." (PMID 30622162, 2019). "On the contrary, apolipoprotein C3 deficiency has been reported to result in diet-induced obesity and aggravated insulin resistance in mice." (PMID 27795741, 2016). "Another case–control study found that the polymorphisms −482 C/T and −455 T/C in APOC3 were associated with nonalcoholic fatty liver disease and insulin resistance." (PMID 25994187, 2015). "The polymorphisms -482 C/T and -455 T/C in APOC3 were associated with nonalcoholic fatty liver disease and insulin resistance." (PMID 25380998, 2014). "One possibility is that secondary factors such as obesity, exercise training, and alcohol use obscured the relationship between the APOC3 polymorphism and insulin resistance in our population." (PMID 21274868, 2011). "Taken together, our findings do not support a model in which a genetic polymorphism in the putative insulin response element of APOC3 leads to increased accumulation of TG in the liver, which in turn results in insulin resistance." (PMID 21274868, 2011). "In summary, we found that transgenic mice with hepatic overexpression of human APOC3 were more prone to develop hepatic steatosis associated with hepatic insulin resistance compared with WT littermates fed the same HFD diet." (PMID 21793029, 2011). "In this contex we hypothize that obesity would expose the association between the APOC3 variants and liver parameters, insulin-resistance and/or lipid levels." (PMID 21663607, 2011). "The common promoter polymorphisms (-455T>C and -482C>T) of the APOC3 gene have been well established as bona fide functional variants, described as an example of insulin resistance at the gene level." (PMID 18096054, 2007). "ApoC3, insulin resistance, and beta-cell dysfunction are independently associated in patients RA." (PMID 35637531, 2022). "Nonalcoholic fatty liver disease (NAFLD) and insulin resistance have recently been found to be associated with increased plasma concentrations of apolipoprotein CIII (APOC3) in humans carrying single nucleotide polymorphisms within the insulin response element of the APOC3 gene." (PMID 21793029, 2011).
Insulin resistance (continued). "Insulin resistance, coupled with hyperglycemia and insufficient insulin, has been shown to raise APOC3 concentrations." (PMID 39684468, 2024). "Hepatic VLDL production and secretion is increased by insulin resistance and altered metabolism of ApoC-3 in CKD further elevates TRLs by overproduction and impaired clearance." (PMID 38413437, 2024). "Understanding how APOC3 interacts with insulin resistance can help researchers create specific interventions for these interconnected metabolic issues." (PMID 39286687, 2024). "Factors such as insulin resistance, dysregulated lipoprotein metabolism, and chronic inflammation elevate APOC3 levels in patients with diabetes." (PMID 39684468, 2024). "ApoC3 is a regulator of lipoproteins and serves as a link between insulin resistance (IR) and beta-cell dysfunction that are present in RA patients." (PMID 38132128, 2023). "Apart from its well-known role in triglyceride metabolism and insulin resistance, new data reveals that APOC3 is connected to various cancers." (PMID 35205837, 2022). "38% of subjects with APOC3 variant alleles had NAFLD, compared to 0% among wild-type homozygotes, and those with NAFLD had marked insulin resistance." (PMID 36035124, 2022). "From a previous study, we understand that abnormal lipid metabolism and insulin resistance affect ApoC3 secretion and recovery rates." (PMID 35453604, 2022). "Insulin response element (IRE) is located in the promoter of the APOC3 gene, and it has been shown that APOC3 induces diabetes and insulin resistance." (PMID 27619170, 2016). "Various studies have revealed that increased APOC3 levels can exacerbate insulin resistance." (PMID 39286687, 2024). "The connection between APOC3 and insulin resistance is complex and significant." (PMID 39286687, 2024). "Numerous studies suggest a close relationship exists between ApoC3 and insulin resistance." (PMID 37689737, 2023). "Our purpose was to study whether ApoC3 is also related to the insulin resistance and beta-cell dysfunction that are present in patients with RA." (PMID 35637531, 2022). "Polymorphisms in APOC3 are also associated with NAFLD and insulin resistance." (PMID 36035124, 2022). "Aligned with the recently identified role of APOC3 in insulin resistance, HOMA-IR, plasma insulin levels, body weight, and adiposity correlated positively with HDL-associated APOC3 levels (r = 0.50, P = 0.00017; r = 0.44, P = 0.0015; r = 0.23, P = 0.048; r = 0.26, P = 0.021, respectively)." (PMID 30622162, 2019). "Here we genotyped two APOC3 variants in 1228 African Americans, 843 European Americans and 426 Hispanics from a multiethnic population based study, the Dallas Heart Study and test for association with HTGC and homeostatic model of insulin resistance (HOMA-IR)." (PMID 21274868, 2011). "To exclude that the presence of insulin-resistance or obesity could mask the possible effects of the APOC3 SNPs, we stratified our subjects on the basis of their insulin-resistance indices, insulin levels, or grade of obesity." (PMID 21663607, 2011). "We did not identify any significant association between APOC3 polymorphisms and fatty liver disease, lipids, and insulin-resistance in obese subjects, thus not confirming the suggested role of these APOC3 gene sequence variants." (PMID 21663607, 2011). "However, whether the high concentration of ApoC3 presents a key role in ovarian dysfunction and local insulin resistance are targets of future research in our next steps." (PMID 37689737, 2023). "Finally, the role of apoC3 in insulin resistance deserves to be mentioned." (PMID 37689737, 2023).
Insulin resistance (continued). "ApolipoproteinC3 (APOC3) is lipoprotein lipase (LPL) inhibitor that induces obesity and develops insulin resistance." (PMID 32899471, 2020). "MR validated the presence of multiple causative risk factors, particularly APOC3, IL-1, IL6, insulin resistance, height, non-fasting glucose, telomere length, HMGCR, and Niemann-Pick C1-Like 1 (NPC1L1)." (PMID 38601677, 2024). "An important correlation between enhanced insulin sensitivity and both plasma ApoC-III and TG suppression was also reported through the effects of the antisense APOC3 inhibitor — volanesorsen (ISIS 304801) — on TG levels and insulin resistance in patients with type 2 diabetes." (PMID 36689070, 2023). "Interestingly, other cohorts of European ancestry did not identify any significant association between APOC3 polymorphisms, NAFLD and insulin resistance." (PMID 36035124, 2022). "Similarly, mice overexpressing APOC3 did not have insulin resistance despite markedly elevated plasma TG levels." (PMID 21274868, 2011). "A recent study including proteomics of potential insulin resistance biomarkers in PCOS women showed that only ApoC3 was flagged as potentially being a diagnostic marker for PCOS-insulin-resistant subjects; however, in this study, ApoC3 was not available in the Somascan panel." (PMID 36980195, 2023).